STAT3 (signal transducer and activator of transcription 3)
Diseases named in the same sentence as STAT3 in open-access papers (continued):
Sharing a sentence is not in itself a finding about the gene and the disease.
cancer (continued). "This was evidenced by the fact that the reduced phosphorylation of STAT3 at the Y705 position by stattic has unleashed these pro-metastatic functions of the cancer cells, leading to the increased presence of CSCs and to an EMT-like phenotype in the cells." (PMID 37190183, 2023). "They showed that CIN induces cGAS-STING which subsequently increases IL-6 expression and activates STAT3 signaling, thereby promoting cancer cell survival and growth." (PMID 36717545, 2023). "STAT3 is known to contribute to ALDHhigh cell homeostasis in various cancer settings and STAT3 activation is a main signaling event after IL-6 stimulation of the cells." (PMID 37460938, 2023). "Another study found that ASX can reduce the expression of STAT3 at the level of protein and mRNA, thereby inhibiting the proliferation of cancer cells." (PMID 36969867, 2023). "It is encouraging and inspiring that during the past decade, more knowledge is gained on how STAT3 is regulated in cancer stem cells and the mechanisms by which STAT3 contributes to poor prognosis in aggressive cancer." (PMID 37642779, 2023). "This strongly suggests that CAD-induced cytosolic acidification sensitizes cancer cells to STAT3 inhibition-induced cell death." (PMID 36807142, 2023). "STAT3 mediates the expression of a variety of genes in response to cell stimuli and serves a promote oncogenesis enhancing cancer cell proliferation, migration, and survival." (PMID 37928418, 2023). "A report revealed that myofibroblast-derived IL-6 and IL-8 activate the NOTCH/HES1 and STAT3 pathways to enhance cancer stemness in colon cancer." (PMID 37046588, 2023). "The Sangerbox database results showed that STAT3 expression status was significantly correlated with immune infiltration score in 27 cancers, illustrating that STAT3 plays a role in immune responses." (PMID 36977736, 2023). "In cancer cells, studies have demonstrated that B-Raf mediates cell death via Signal Transducer and Activator of Transcription 3 (STAT3)." (PMID 37108645, 2023). "The combination of ROS, reactive nitrogen species (RNS), IL-6, and JAK induces DNA damage leading to genetic instability through the STAT-3 pathway, promoting cancer cell proliferation and angiogenesis." (PMID 37749514, 2023). "The activation of the Janus kinase/signal transducer and activator of the transcription (JAK2/STAT3) signaling pathway promotes the proliferation, migration, and invasion of cancer cells." (PMID 37009004, 2023). "Exactly, CCDN1, a cell cycle regulator that is required for G1/S transition, was reported as a STAT3 target in several cancer types." (PMID 38001065, 2023). "The JAK2/STAT3 signaling pathway has been shown to play a critical role in injury and cancer in multiple systems." (PMID 37132754, 2023). "STAT3 is located intracellularly, downstream many kinases at an exchanging point of the most important signaling pathways involved in cancer." (PMID 36902166, 2023). "To better understand the connections among differentially expressed genes in the Cancer Hallmark pathway analysis, we performed KDDN analysis to identify novel connections induced by SI or JGT in the IL6/JAK/STAT3 and OXPHOS pathways." (PMID 36980301, 2023). "In this way, the signaling inhibition of NFkB by STAT3 means that NFkB cannot stimulate anti-apoptotic genes and suppress pro-apoptotic ones, as usually happens during cancer progression." (PMID 37445915, 2023). "Lymphotoxin-producing Breg cells can be recruited by CXCL13, which stimulate the lymphotoxin receptor on cancer cells, induce IKKα nuclear translocation and STAT3 activation, and promote cancer metastasis." (PMID 37868967, 2023). "miR-3184-5p has been shown to bind X-box binding protein 1 (XBP-1), a potential transcription activator of STAT3 that plays a critical role in cancer transformation and carcinogenesis." (PMID 37514090, 2023). "STAT3 is known to play an important role in the maintenance of cancer-stem-cell-like subpopulations in many cancer types." (PMID 37190167, 2023).
cancer (continued). "We investigated the effects of natural compounds on MDCS-induced STAT3 activation in SBC-3 cells to identify candidate agents for the inhibition of macrophage-induced cancer proliferation." (PMID 36961655, 2023). "Aberrant STAT3 expression has been previously shown to facilitate the malignant development of multiple human cancers." (PMID 37628777, 2023). "Combined multi-omics and biochemical analyses indicate an elevated PI3K/AKT/p65 driven cell survival and cytokine production in rCAFs, while rCAF-secreted TGFα promotes cancer cell chemoresistance by activating EGFR/Src/STAT3 survival signaling axis." (PMID 37821657, 2023). "The molecular functions of STAT3 have been extensively discussed in malignant tumours, mainly including its influence on the cell cycle, inflammatory process, and angiogenesis." (PMID 36979673, 2023). "Effective inhibition of IL-6-induced signaling and transcription activator 3 (STAT3) phosphorylation can significantly downregulate the invasive ability of cancer cells." (PMID 37990309, 2023). "Expression of PD-L1 in cancer cells is regulated by multiple signaling pathways, including transcription factors, such as STAT3, HIF1α and MYC." (PMID 37928424, 2023). "We noticed that WZ26 significantly decreased STAT3 and dreadfully induced ROS levels, which regulated mitochondrial apoptosis and inhibited cancer cell growth in CCA cancer cells." (PMID 36647192, 2023). "In recent years, research has shown that interleukin 6 (IL6) induces EMT of cancer cells by STAT3 activation." (PMID 37651362, 2023). "STAT3 is constitutively activated in many cancers and its inhibition is being explored in clinical trials." (PMID 37686362, 2023). "Several closely related mechanisms can contribute to the transformation of acinar cell metaplasia into cancer: oxidative stress, activation of inflammatory pathways (such as Cyclooxygenase-2 (Cox2)), and activation of NF-κB and STAT3 pathways." (PMID 36765725, 2023). "Distinguishing between the two isoforms and their active forms is crucial for STAT3-related cancer diagnosis and therapy." (PMID 37097001, 2023). "Because of their pro-tumorigenic role, STAT3 inhibitors have been developed as anticancer agents in various human cancers." (PMID 37242454, 2023). "The mutations leading to increased cancer cell survival, discussed earlier, are engaged in the activation of oncogenic pathways, including WNT/beta-catenin, STAT3, PI3K/PTEN/AKT/mTOR, RAS/RAF/MAPK or NFκB." (PMID 37427115, 2023). "The top Cancer Hallmark pathways enriched in the SI rats, compared with the group-housed rats, included IFNα, IFNγ, and inflammatory responses, and IL6/JAK/STAT3 and TNFα signaling via NFκB." (PMID 36980301, 2023). "Overall, we found that STAT3 has a good predictive value for cancer prognosis, drug resistance, and immunotherapy." (PMID 36977736, 2023). "Chronic inflammation occurs due to persistent STAT3/STAT5 activation which leads to increased susceptibility of healthy cells and the development of cancer." (PMID 37803407, 2023). "To understand the mechanism by which PA-CM induced apoptosis in CCA cells, we focused on JAK2/STAT3 signaling, which plays an important role in the growth and survival of many cancers, including CCA." (PMID 38132108, 2023). "Signal transducer and activator of transcription 3 (STAT3) is responsible for angiogenesis proliferation, apoptosis, and basal homeostasis; hallmarks for cancer development including GC." (PMID 37609398, 2023). "OPB-33121 and OPB-51602 trials demonstrated the efficacy of STAT3 inhibition in cancer treatment, but have to be terminated due to poor pharmacokinetics and toxicities." (PMID 39872303, 2023). "Recent evidence suggests that STAT3 is a regulatory node of cancer-related inflammation and a regulator of immune checkpoint proteins." (PMID 37063281, 2023).
cancer (continued). "It is believed that CUR influences the expression of different genes in the cancer cells themselves, such as NF‐kB, STAT‐3 and AP‐1, as well as protein kinases, including MAPK and enzymes such as COX and LOX." (PMID 37697969, 2023). "STAT3 also plays an important role in cancer cell survival, including PEL cells, by regulating the expression of molecules such as BIRC5." (PMID 37511362, 2023). "These cancer cells were reported to have enhanced cell migration, invasion capability and high metastatic potential, and inhibition of STAT3 led to sensitization of all those anoikis-resistant cells." (PMID 36902166, 2023). "VaM effectively inhibits cancer cell viability and proliferation, induces apoptosis, and regulates cell cycle progression through the STAT3 signaling pathway." (PMID 37569363, 2023). "Several TrxR-1 inhibitors also block the signal transducers and activators of transcription 3 (STAT3) activity via accumulation of oxidized STAT3, which blocks STAT3-dependent transcription and induces cancer cell death." (PMID 37446140, 2023). "In this study, multiple databases were used in a comprehensive pan-cancer analysis to provide a rationale for STAT3 as a broad-spectrum immunotherapy target in oncology." (PMID 36977736, 2023). "There is accumulating evidence that STAT3 is a significant regulator of the stemness phenotype in a variety of cancers, including OvCa." (PMID 37173951, 2023). "STAT3 signaling is involved in multiple cancer cell hallmarks, including proliferation, anti-apoptosis, angiogenesis, invasion and metastasis, immunosuppression, and drug resistance." (PMID 36672335, 2023). "In conclusion, the FGF3/FGFR1/STAT3 signaling pathway is one of the mechanisms by which FGF3 promotes cancer." (PMID 37496658, 2023). "A growing number of studies substantiate that STAT3 can affect the survival, proliferation, angiogenesis, and metastasis of cancer cells via regulating the expression of different genes, thereby promoting the malignant development of cancer." (PMID 37231451, 2023). "Alternatively, STAT3 inhibition through siRNA suppressed cancer cell proliferation and resensitized neuroendocrine tumors to mTOR inhibitor Everolimus treatment." (PMID 37784082, 2023). "Significantly, sgRNA-PRMT6#1 cancer cells displayed diminished nuclear STAT3 expression compared to sgRNA-Control cells." (PMID 37813837, 2023). "In monocytes and macrophages, cancer EVs can activate Toll-like receptor-mediated signaling cascade, triggering NFκB- and STAT3-mediated production of proinflammatory cytokines – IL-6, IL-8, IL-1β, CCL2, G-CSF, and TNF-α." (PMID 37397375, 2023). "Taken together, the Western blot analysis results suggested that 11c treatment inhibits the constitutive and IL-6-induced STAT3 phosphorylation in cancer cells." (PMID 37103357, 2023). "Napabucasin, a drug specifically developed to target STAT3 in cancer, is underpinned by relatively comprehensive phenotypic and mechanistic studies." (PMID 37953954, 2023). "The gp130 family members, IL-11, IL-6, OSM, and LIF (upregulated in the LM) potentially impact skeletal muscle wasting by inducing the STAT3 signaling pathway in the preclinical model of cancer cachexia." (PMID 36774484, 2023). "Silencing of STAT3/STAT1 resulted reduced MDR frequency in cancer cells, suggesting the involvement of both STAT signaling in MDSC-induced generation of chemo-resistance." (PMID 38304256, 2023). "Our study shows that inhibition of STAT3 phosphorylation significantly reduces the regulatory effect of IL13 on cancer cell stemness." (PMID 37534250, 2023). "Overactivition of STAT3 under inflammatory and cancer conditions has led to suggestions that it is a potential therapeutic target." (PMID 36831081, 2023). "Compared with wild-type group, the NF-κB mutation significantly diminished STAT3 promoter activity, and this inhibitory effect was further extended in METTL3 knockout cancer cells." (PMID 38001065, 2023).
cancer (continued). "Combined, these results support previous claims that targeting DHFR decreases STAT3 transcriptional activity and point towards STAT3 being involved in the anti-cancer mechanism of these DHFR inhibitors." (PMID 36837770, 2023). "Recent studies have shown that interleukin 6 (IL-6) and the major downstream effector signal transducer and activator of transcription 3 (STAT3) are pro-tumorigenic agents in a variety of human cancers, including PDAC." (PMID 36495330, 2023). "By directly binding to the promoter of PD-L1, the S STAT3 regulates PD-L1 expression in a plethora of cancers, such as T-cell lymphoma, breast cancer, nasopharyngeal carcinoma, osteosarcoma, and gastric cancer." (PMID 36672335, 2023). "The signal transducer and activator of transcription 3 (STAT3) is a transcription factor that plays a critical role in promoting the survival, proliferation, and immune evasion of cancer cells." (PMID 37569363, 2023). "Targeting the STAT3 signaling pathway has been used as a promising therapeutic strategy in cancer, and preclinical and clinical studies on STAT3 inhibitors are ongoing." (PMID 37121974, 2023). "In normal cells, STAT3 activity is regulated to maintain a transiently active state, but its activity becomes dysregulated in cancer due to the atypical activation of many tyrosine kinases within cancer cells." (PMID 39872303, 2023). "Emerging evidence suggests that XIST and STAT3, by mutually regulating each other, form a double positive feedback loop that promotes inflammation and cancer development." (PMID 36922677, 2023). "In the Cancer Hallmark pathway analysis, IFNα, IFNγ, inflammatory responses, and IL6/JAK/STAT3 signaling were suppressed significantly by JGT in tamoxifen-treated GH rats." (PMID 36980301, 2023). "STAT3 encourages the growth of cancer cells, immunological suppression, angiogenesis, the spread of metastatic disease, and the emergence of therapeutic resistance." (PMID 37651362, 2023). "Resveratrol, a stilbenoid commonly found in various berries, grapes, and peanuts, has shown anti-cancer activity in multiple cancer types by modulating the STAT3 signaling pathway." (PMID 37173951, 2023). "Dihydrofolate reductase (DHFR) is an established anti-cancer drug target whose inhibition disrupts folate metabolism and STAT3-dependent gene expression." (PMID 36837770, 2023). "Many studies have proved that IL-10 derived from cancer can activate MDSCs through STAT3 pathway, and in our study, we found that MDSCs are accompanied by a large amount of IL-10 secretion in the process of inducing B10 cell differentiation." (PMID 35725835, 2023). "STAT3 plays a crucial role in multiple human cancers, especially in GBM, and it is in an over-activated state that is often associated with poor clinical prognosis." (PMID 37057281, 2023). "Studies have also demonstrated that IL-10 stimulates the epithelial-mesenchymal transition (EMT) process in cancer cells and enhances cancer cell proliferation through the STAT3-NF-κB-IL-10 signaling axis." (PMID 37637038, 2023). "IL-6/gp130/STAT3 signaling is involved in cancer progression and drug resistance in various human cancers, including ovarian, breast, gastric, and colon." (PMID 36495330, 2023). "The signal transducer and activator of transcription 3 (STAT3) plays a vital role in cancer progression." (PMID 37173892, 2023). "The expression of p21 and p63 has been reported to be regulated downstream of STAT3 using cancer cells and cell lines." (PMID 37846594, 2023). "The expression cor-relationships between METTL3 and its targets, including JAK1, VEGFA, CCND1, and STAT3, was positive in almost all analyzed cancer types." (PMID 38001065, 2023). "Taken together, these results indicate that the expression of STAT3 differs between normal and cancer tissues in the vast majority of cancers; in particular, STAT3 protein expression is significantly higher in cancer than that in normal tissues." (PMID 36977736, 2023).
cancer (continued). "Research on cancer therapy indicates targeting STAT3 as a potentially important curative approach toward malignancies." (PMID 37109658, 2023). "And the study provided undeniable evidence that structurally activated STAT signaling pathway, particularly STAT3, played an important role in cancer progression by preventing apoptosis." (PMID 37660003, 2023). "STAT3 dysfunction appears to promote the proliferation, migration, and invasion of malignant tumors." (PMID 36720310, 2023). "Abnormal STAT3 activation is a critical factor in the occurrence and development of cancer by promoting malignant cell proliferation, migration, and metastasis." (PMID 37465088, 2023). "Both IL-6 and IL-8 have been demonstrated to inhibit antitumor CD8 T-cell responses via recruitment of immunosuppressive myeloid cells or STAT3 activation and arginase-I-mediated suppressive functions of MDSCs in genitourinary and other human cancers." (PMID 38259453, 2023). "Multiple analyses show that STAT proteins, for instance, STAT3, display persistent activity in various human cancer cells and promote the advancement of cancer." (PMID 37970406, 2023). "Evidence along this line came from the fact that inhibition of STAT3 inhibits cancer cells’ proliferation and selectively induces apoptosis in cancer cells." (PMID 36831081, 2023). "A part from the cross-talk between them, NRF2 and STAT3 interplay controls a variety of processes and pathways that play a key role in cancer as well as in several other diseases." (PMID 37000324, 2023). "It is becoming increasingly clear that CIN and DNA damage can trigger IL-6/STAT3 signaling in various cancer types, including breast cancer and ovarian cancer." (PMID 37561163, 2023). "STAT3 interacts with several cellular pathways involved in cancer cell proliferation, progression and immune dysfunction." (PMID 37000324, 2023). "Preclinical studies aiming to modulate the expression and/or function of STAT3 have demonstrated important roles of STAT3 in the progression of multiple cancers, including CRC." (PMID 37686695, 2023). "Numerous studies have demonstrated that suppression of the JAK/STAT3 pathway by inhibitors can inhibit cancer cell invasion and promote apoptosis." (PMID 37894738, 2023). "In summary, our study uncovers that PRRG4 promotes the invasion and metastasis of cancer cells by modulating mitochondrial function through the Src-STAT3-POLG axis." (PMID 38102641, 2023). "HSP90, favoring active STAT3/5 localization and interaction with multiple kinases in the cytosol, is a potential therapeutic target in various kinds of cancers." (PMID 36927693, 2023). "This relationship between FAP and STAT3 (each is a therapeutic target in cancer) can be taken into account when creating more effective treatments in oncology." (PMID 36825204, 2023). "The exposure of PANC-1 pancreatic cancer cells to a combined dose of SFN and BITC displayed increased selective killing of cancer cells and the inhibition of STAT3 tyrosine phosphorylation compared to their individual treatments." (PMID 36765652, 2023). "Aberrantly activated JAK2/STAT3 is frequently detected in many cancer diseases that are usually refractory to standard chemotherapy." (PMID 37686148, 2023). "Recent studies have uncovered an interdependence of PI3K and STAT3 signaling in cancer cells; in particular, STAT3 was phosphorylated at Tyr705 and activated in a PI3K-dependent manner." (PMID 36413402, 2023). "It has been shown that patients with TNBC and high OSM expression have a greater abundance of cells with a cancer stem cell (CSC) phenotype due to OSM/STAT3/SMAD3 signaling, which promotes growth of the tumor and leads to poor clinical outcomes for patients." (PMID 37841259, 2023). "In contrast, in most cancer processes, hyperactivity of STAT3 is commonly correlated with a poor clinical prognosis." (PMID 36714534, 2023).